COMP (cartilage oligomeric matrix protein)
Diseases named in the same sentence as COMP in open-access papers (continued):
Sharing a sentence is not in itself a finding about the gene and the disease.
cancer (74 papers, 2016 to 2026). A tumor composed of atypical neoplastic, often pleomorphic cells that invade other tissues. "The expression of COMP in cancer cells in the entire cohort was associated with shorter overall survival (OS) (p = 0.013) and recurrence-free survival (RFS) (p = 0.029), while COMP expression in the stroma was correlated with shorter RFS (p = 0.042)." (PMID 38563861, 2024). "COMP expression in the cancer cells was also associated with less infiltrating CD138+ B-cells (p = 0.038) and activated FoxP3+ T-cells (p < 0.001)." (PMID 38563861, 2024). "Further bioinformatic analysis revealed that COMP was significantly upregulated in various cancers, especially in advanced CRCs, and regulated the immune infiltration, especially M2 macrophages and cancer-associated fibroblasts in CRCs." (PMID 36551305, 2022). "Among the three cell types promoting T cell exclusion, only cancer-associated fibroblasts were positively associated with the expression levels of both COMP and its co-expressed genes." (PMID 36551305, 2022). "Subsequently, the connections of COMP expression with the cancer immunity cycle and signaling pathways associated with ICB treatment were investigated." (PMID 36671447, 2022). "In some bioinformatics studies, COL5A2 and COMP have been found to be associated with cancers including GC." (PMID 34899080, 2021). "We then set out to investigate the molecular mechanism underlying the effect of COMP on the metabolism of cancer cells." (PMID 29228690, 2017). "Furthermore, we examined the associations of COMP expression in cancer cells and in the stroma, respectively, with overall survival (OS) and recurrence-free survival (RFS)." (PMID 38563861, 2024). "Furthermore, high levels of COMP expression were associated with lower levels of PD-L1 expression by both cancer cells and immune cells." (PMID 38563861, 2024). "Elevated COMP levels recently linked to worse overall survival in multiple cancer types." (PMID 37838792, 2023). "Also, high levels of COMP expression in the cancer cells were associated with fewer CD56+ NK cells (p=0.044)." (PMID 37207219, 2023). "However, when analyzing COMP IHC expression in LNM cancer cells and stroma, there were significant associations with PFS and OS where a high IHC COMP expression was associated with a worse outcome (PFS, p = 0.040 and OS, p = 0.041)." (PMID 34884987, 2021). "Therefore, mitochondrial function and oxidative phosphorylation may play a role in the increased progression of COMP treated cells and radiation resistance, which has previously been implicated in cancer drug and radio-resistance." (PMID 40141111, 2025). "Therefore, we hypothesized that COMP expression may also be elevated when patients developed BC or TC, thereby increasing the risk of another primary cancer through the same pathogenic pathway." (PMID 37229458, 2023). "Therefore, COMP may promote the progression of TC and BC, thereby increasing the risk of secondary primary cancer." (PMID 37229458, 2023). "However, whether RvD1 inhibits paracrine of cancer-associated fibroblasts (CAFs)-derived COMP to prevent epithelial-mesenchymal transition (EMT) and cancer stemness in HCC remains to be elucidated." (PMID 30999932, 2019). "COMP has also been shown to initiate cancer stem cells through the activation of Jagged1-Notch3 signaling." (PMID 40592939, 2025). "The aim of this study was to examine the roles of COMP in cartilage but also in tendon and vascular tissues, in tissue fibrosis and in cancer." (PMID 41009743, 2025). "T1 and T2 clusters exhibited similar marker genes, including POSTN, COMP, and THBS2, which are markers associated with cancer-associated fibroblasts, showing heightened expression." (PMID 39670859, 2025). "COMP regulates the Complement system and is involved in both the development of and defense against cancer." (PMID 41009743, 2025).
cancer (continued). "Irradiated GDC0941 and COMP-treated GDC0941 and COMP-treated cells exhibited lower protein expression of ABCC3, a protein involved in treatment resistance in NSCLC and other cancers, and MT-CO1, a mitochondrial protein associated with cancer progression." (PMID 40141111, 2025). "Irradiated PP2 and COMP-treated A549 cells exhibited lower protein concentration of DCXR, a protein associated with increased proliferation and progression of various cancer types." (PMID 40141111, 2025). "Some ongoing studies are focusing on highly expressed genes like secreted frizzled-related protein 4 (SFRP4) and cartilage oligomeric matrix protein (COMP), both of which have been shown to play a role in cancer invasion and metastasis." (PMID 40710181, 2025). "Future studies need to clarify if this is only a mechanism that observed in cancer of the gastrointestinal tract, or if it is universally observed in COMP expressing tumors." (PMID 38563861, 2024). "TME components such as COMP play major roles in cancer progression and aggressiveness, making them an attractive target for cancer therapeutics." (PMID 38615020, 2024). "Pathways previously identified as being involved in the oncogenic effect of COMP in other types of cancer, such as Notch, TGF-β, WNT, PI3K were found to be affected." (PMID 38563861, 2024). "COMP protects cancer cells from endoplasmic reticulum stress-mediated apoptosis and induces a metabolic switch, i.e., the Warburg effect." (PMID 38615020, 2024). "We assessed the potential mechanism by which ER-localized COMP renders cancer cells resistant to apoptosis by influencing the intracellular calcium homeostasis." (PMID 38965233, 2024). "It is possible that in these cancer types, the expression of COMP in the stroma is of greater significance." (PMID 38965233, 2024). "CH can suppress such EMT related factors (like snail, slug, and twist) via inhibition of cartilage oligomeric matrix protein (COMP) expression and helps to maintain cancer cells in a less invasive state, thus considered as a potential therapeutic target." (PMID 38966181, 2024). "We observed that the expression of COMP by cancer cells was a prognostic marker of patients' OS and RFS." (PMID 38563861, 2024). "The analysis of COMP expression in pairs of primary tumors and lymph nodes with metastasis showed that most primary tumors lost COMP expression when the cancer cells metastasized to local lymph nodes." (PMID 38563861, 2024). "COMP was expressed (score 1-3) in the cancer cells in 39.5% of the patients and in the stroma in 60% of the patients." (PMID 37207219, 2023). "A similar negative association was evident when we compared the PD-L1-expressing cancer cells with the expression of COMP in the stroma." (PMID 37207219, 2023). "In conclusion, we confirmed in a large cohort of CRC patients that expression of COMP in both cancer cells and in stroma correlates with TNM stage and grade of differentiation." (PMID 37207219, 2023). "The underlying molecular mechanism involves the activation of Notch3 by its ligand Jagged1 bridged together by COMP, which leads to a generation of a higher proportion of cancer stem cells." (PMID 37207219, 2023). "The predictive effects of COMP expression on cancer metastasis and patient survival in iCCA were assessed using univariate and multivariate analyses." (PMID 37838792, 2023). "The elevated levels of COMP expression by the cancer cells (HR 1.190, p=0.0016) and in stroma (HR 1.295, p<0.001) were predictive of worse OS of the CRC patients." (PMID 37207219, 2023). "In recent years, COMP has emerged as a novel regulator of cancer progression in several different types of cancer." (PMID 37207219, 2023). "Our immunohistochemical staining showed clear expression of COMP in cancer cells but also extensive deposits in the extracellular matrix." (PMID 37207219, 2023).
cancer (continued). "CD56+ NK cells were infiltrating the rectum tumors less when COMP was highly expressed by the cancer cell and in the stroma (p<0.001 cancer cells and p<0.001 stroma)." (PMID 37207219, 2023). "CD68+ macrophages also infiltrated less in the presence of high COMP expression by the cancer cells (p=0.033)." (PMID 37207219, 2023). "CRC patients with rectum primary tumors presented a similar negative association between the expression of PD-L1 by the immune cells and the expression of COMP both by the cancer cells and in the stroma." (PMID 37207219, 2023). "When high levels of COMP were evident in both cancer cells and the stroma, fewer infiltrating CD56+ NK cells were detected (p=0.022 cancer cells and p=0.002 stroma)." (PMID 37207219, 2023). "This is supported by the observation that while COMP expression from both cancer cells and in stroma correlated with immune exclusion, only COMP in stroma correlated with collagen density." (PMID 37207219, 2023). "Expression of COMP by cancer cells was denoted in 40.5% of patients with tumors in the right colon, in 38.3% of patients with tumors in the left colon, and in 39.9% of patients with tumors in the rectum." (PMID 37207219, 2023). "The pan-cancer analysis also revealed a positive correlation between the DNA methylation level of COMP and the neutrophils that existed in most cancers." (PMID 36551305, 2022). "Further GSEA analysis indicated that the TGF-β signaling pathway and cancer-related pathway were significantly activated in CRC tissues with high COMP expression levels compared with the low COMP expression group." (PMID 36551305, 2022). "Herein, we found that COMP was favorably connected with the activities of numerous phases in the cancer immune cycle and inversely connected with immunotherapy-related signs." (PMID 36671447, 2022). "COMP has been reported to be implicated in the EMT and other well-known cancer cell signaling pathways, such intracellular calcium homeostasis, Notch3, Akt, MEK/ERK, etc.." (PMID 36671447, 2022). "Recent exciting achievements have implied that COMP is an important gene contributing to other diseases, such as cancer/malignancy, cardiovascular diseases, and fibrosis." (PMID 36012514, 2022). "Based on the expression profiles of 5 genes, PCA showed that normal and cancer samples were clearly separated, with COMP, ICA1, and PSMB1 contributing to PC1 and ACAA1 and with SCGB2A1 contributing to PC2." (PMID 35909904, 2022). "Our findings indicated that COMP correlated positively with the majority of cancer immunity cycle phases, while inversely with almost all ICB-treatment-related signaling pathways." (PMID 36671447, 2022). "This is consistent with other EMT pathway genes in the skin; COMP, CTHRC1, ECM2, FBN1, LOX, and SPARC were all upregulated in samples with a mutation in a cancer gene." (PMID 36531005, 2022). "The findings reveal that COMP was positively correlated with a majority of immune inhibitors and stimulators in several cancers, with TNFSF4, an immune stimulator, and HAVCR2, an immune inhibitor, exhibiting the strongest correlation with COMP." (PMID 36551305, 2022). "COMP expression levels in cancer tissues are significantly higher than in neighboring normal tissues." (PMID 36012514, 2022). "Cartilage Oligomeric Matrix Protein (COMP) controls the cancer stem cell population via increasing Notch3 and Jag-ged1 interaction which results in increased Notch3 signaling activation." (PMID 36017236, 2022). "For survival analyses, a combined variable was used that assessed the COMP IHC expression in both the cancer cells and stroma." (PMID 34884987, 2021). "There were 20 cells expressing COMP, of which only 3 cells were from normal tissues and 17 cells were from cancer tissues." (PMID 34899080, 2021). "McNemar’s analyses were used for the evaluation of concordance and discordance of IHC COMP expression in cancer cells and stroma." (PMID 34884987, 2021).
cancer (continued). "A similar trend was observed between the levels of serum COMP and the expression of COMP by the cancer cells of DM." (PMID 34884987, 2021). "Further studies are needed to thoroughly dissect the relations between ECM composition and COMP expression by the metastatic cancer cells." (PMID 34884987, 2021). "Given that apoptosis inhibition is an important feature of cancer, we measured levels of the antiapoptotic protein Bcl-2 and of the proapoptotic proteins Bax and caspase-3 to further explore the role of COMP in apoptosis of PTC cells." (PMID 33613749, 2021). "COMP expression by cancer cells affects their metabolism, metastases, and the abundance of cancer stem cell populations." (PMID 34884987, 2021). "Most importantly, in all of the types of cancer that have been studied so far, high expression of COMP has been correlated with reduced survival of the patients." (PMID 34884987, 2021). "It has been already established that COMP expression in cancer cells increases their invasive potential, alters metabolism (Warburg effect), and renders them resistant to apoptosis." (PMID 34884987, 2021). "Further, COMP expression in cancer cells correlated positively with the presence of lymph node metastases and estrogen/progesterone receptor positivity." (PMID 34884987, 2021). "From the remaining paired samples, more LNM lost the expression of COMP (21% and 23%, respectively) than gained it (7% for both the cancer and stromal cells)." (PMID 34884987, 2021). "Further, COMP facilitates the interaction between Notch3 and its ligand Jag1, which leads to the generation of a larger population of cancer stem cells." (PMID 34884987, 2021). "COMP encodes cartilage oligomeric matrix protein, which is also an ECM protein that enhances the invasion of cancers through integrin binding." (PMID 32175330, 2020). "COMP expression leads to a larger cancer stem cell population in vitro and in vivo, as a result of Notch3 pathway activation." (PMID 31737569, 2019). "All these findings indicated that the upregulation of COL3A1 and COMP is closely related to the occurrence and development of cancer." (PMID 29967488, 2018). "It is likely that COMP expression can be found in a wide range of cancers where the protein exerts effects similar as those observed here." (PMID 29228690, 2017). "COMP is an extracellular matrix protein that is now found to be expressed by cancer cells, and which aggravates malignant disease." (PMID 29228690, 2017). "Since COMP expression protects cancer cells against apoptosis, we investigated wether this protection was due to impaired Ca2+ signalling." (PMID 29228690, 2017). "Most interestingly, we show that the mechanism by which COMP increases the malignancy of cancer cells is related to its effect on intracellular Ca2+ metabolism, providing the cells with resistance to apoptosis and induces a metabolic switch." (PMID 29228690, 2017). "Importantly, suppressing COMP counteracted the cancer-promoting effects triggered by CRLF1 overexpression." (PMID 42122189, 2026). "COMP is a cancer biomarker and is useful in staging the progressive/poor prognosis/cancer remission phases of diseases including colon, prostate, pancreas, stomach and rectal adenocarcinomas, lymphoid neoplasms, diffuse large B-cell lymphoma, and kidney and ovarian adenocarcinomas." (PMID 41009743, 2025). "COMP has roles in the development of hepatocellular, colorectal, adenocarcinoma, urothelial, adenoma, gastric and breast cancer." (PMID 41009743, 2025). "In addition to its roles as a biomarker of cartilage destruction, COMP is also a serum biomarker that can be an indicator of cancer progression/poor prognosis and organ/tissue fibrosis." (PMID 41009743, 2025). "This suggests that COMP may be an appropriate therapeutic target to focus on in the treatment of this cancer type." (PMID 41009743, 2025).
cancer (continued). "Thus, COMP expression is directly associated with elevated proliferation, metastatic potential in NSCLC, and poor patient outcomes in other cancer types." (PMID 40141111, 2025). "COMP also promotes cancer cell stemness by increasing the interaction between Notch3 and its ligand Jagged1, resulting in increased activation of Jagged1-Notch3 signaling and cross-reactivity with other important cancer-related pathways, such as AKT and β-catenin." (PMID 38965233, 2024). "COMP expression was scored manually in the cancer cells and in stroma, respectively." (PMID 38563861, 2024). "Studies have provided compelling evidence of COMP’s multifaceted role in cancer biology." (PMID 38615020, 2024). "Since COMP is a secreted protein that interacts with the surrounding ECM but also rebinds to the surface of cancer cells, we queried whether the secreted COMP or the intracellular COMP protects the cancer cells from apoptosis." (PMID 38965233, 2024). "Our experiments demonstrated that treatment with some of the components of OA such as IL-1α and COMP was not the sole contributing factor causing the cancer to grow and migrate." (PMID 38892202, 2024). "Furthermore, similar observations regarding infiltrating immune cells were made across the entire cohort when COMP expression in tumors (including cancer cells and stroma) was evaluated using the Qupath software." (PMID 38563861, 2024). "Among these, THBS2 and COMP were upregulated in cancer tissue." (PMID 38827236, 2024). "Notably, COMP expression by the cancer cells was correlated with the expression of COMP in stroma (n = 152, p < 0.001, Spearman's ρ = 0.503)." (PMID 38615020, 2024). "Lastly, our study highlights a novel pathway that may further elucidate mechanisms for cancer promotion in the setting of OA, which could provide a therapeutic treatment strategy by blocking COMP, yet more work is still required." (PMID 38892202, 2024). "Furthermore, in the entire cohort, COMP expression by cancer cells served as a prognostic marker of shorter OS (p = 0.015) and RFS (p = 0.027), independently of PD-L1 expression on cancer cells and immune cells, PD-1 expression on immune cells, and MMR status." (PMID 38563861, 2024). "Comparison of the expression of COMP in the stroma of the primary tumors with the expression of cancer cells in the lymph node metastasis showed that 2 pairs had gained expression, 4 pairs had retained expression, and 26 pairs had lost the expression of COMP in lymph node metastases (p < 0.001)." (PMID 38563861, 2024). "In addition, total COMP expression in tumors (including cancer cells and stroma) expressed as percentage of positive cells was analysed using Qupath software." (PMID 38563861, 2024). "Similarly, less activated FoxP3+ T-cells (cancer cells: p = 0.001, stroma: p = 0.020) infiltrated the tumors when COMP was expressed by both cancer cells and stroma." (PMID 38563861, 2024). "Interestingly, COMP expression was negatively correlated with PD-L1-positive cancer cells and immune cells." (PMID 37207219, 2023). "Likewise, COMP is upregulated in bladder and colorectal cancers and is indicative of worse prognosis for the cancer patient." (PMID 36765749, 2023). "Interestingly, PD-L1-expressing immune cells were negatively correlated with the expression of COMP by the cancer cells and in the stroma (p<0.001)." (PMID 37207219, 2023). "Tumors in the collagen-COMP high groups had fewer infiltrating T-cells that were CD3+ (p<0.001 for both cancer cells and stroma), CD8+ (p<0.001 cancer cells and p=0.002 stroma), and FoxP3+ (p<0.001 for both cancer cells and stroma) compared to tumors in the collagen-COMP low groups." (PMID 37207219, 2023). "In periampullary adenocarcinoma, cancer cells and the surrounding stroma exhibit high COMP levels." (PMID 36765749, 2023). "Furthermore, we used unbiased quantitative evaluation of COMP expression with the QuPath software calculating the percentage of total (cancer cells and stroma) positive cells." (PMID 37207219, 2023).